AP1G1 (adaptor related protein complex 1 subunit gamma 1)
Description:
Subunit of clathrin-associated adaptor protein complex 1 that plays a role in protein sorting in the late-Golgi/trans-Golgi network (TGN) and/or endosomes. The AP complexes mediate both the recruitment of clathrin to membranes and the recognition of sorting signals within the cytosolic tails of transmembrane cargo molecules. In association with AFTPH/aftiphilin in the aftiphilin/p200/gamma-synergin complex, involved in the trafficking of transferrin from early to recycling endosomes, and the membrane trafficking of furin and the lysosomal enzyme cathepsin D between the trans-Golgi network (TGN) and endosomes.
Synonyms: ADTG; CLAPG1; USRISD
Tractability: Antibody: UniProt places it where antibodies can reach, with high confidence. PROTAC: ubiquitination databases record sites on it; its protein half-life has been measured.
Gene: Protein-coding gene on chromosome 16 (71,729,000 to 71,809,201, reverse strand). Ensembl gene ENSG00000166747.
Subcellular location: Golgi apparatus; Cytoplasmic vesicle, clathrin-coated vesicle membrane; Cytoplasm; Cytoplasm, perinuclear region; Cytoplasmic vesicle, clathrin-coated vesicle; Membrane, clathrin-coated pit
Subcellular location (Human Protein Atlas): Golgi apparatus; Vesicles; Cytosol
Pathways (Reactome):
Vesicle-mediated transport: Golgi Associated Vesicle Biogenesis; Lysosome Vesicle Biogenesis
Disease: Nef mediated downregulation of MHC class I complex cell surface expression
Immune System: MHC class II antigen presentation
Gene Ontology:
Molecular function: GTP-dependent protein binding; kinesin binding; protein binding; small GTPase binding; clathrin adaptor activity; collagen binding
Biological process: endosome to melanosome transport; Golgi to lysosome transport; positive regulation of natural killer cell degranulation; positive regulation of natural killer cell mediated cytotoxicity; basolateral protein secretion; Golgi to vacuole transport; melanosome assembly; melanosome organization; platelet dense granule organization; vesicle-mediated transport; intracellular protein transport; synaptic vesicle budding from endosome; synaptic vesicle endocytosis
Cellular component: clathrin-coated vesicle; cytoplasm; cytosol; Golgi apparatus; membrane; recycling endosome; AP-1 adaptor complex; clathrin-coated vesicle membrane; cytoplasmic vesicle membrane; early endosome; Golgi membrane; lysosomal membrane; trans-Golgi network membrane; clathrin-coated pit; intracellular vesicle; membrane coat; perinuclear region of cytoplasm; presynapse; trans-Golgi network
Genetic constraint (gnomAD): Loss-of-function variants: 4 observed, 81.02 expected, observed/expected ratio (o/e) 0.0494, 90% interval 0.023 to 0.11. The upper end of that interval is the gene's LOEUF score, 0.11, which puts it in group 1 of 6, group 1 being the genes least tolerant of losing a copy. Missense variants: 637 observed, 881.27 expected, observed/expected ratio (o/e) 0.72, 90% interval 0.68 to 0.77. Synonymous variants: 324 observed, 313.92 expected, observed/expected ratio (o/e) 1.03, 90% interval 0.94 to 1.13.
Gene-disease validity (ClinGen):
ClinGen rates the evidence that AP1G1 causes each of these diseases.
complex neurodevelopmental disorder (autosomal dominant): Strong. A disorder that involves more than one phenotype associated with the central nervous system, including but not limited to intellectual disability, autism, and seizures (epilepsy).
complex neurodevelopmental disorder (autosomal recessive): Limited.
Homologues: Orthologues: chimpanzee AP1G1 (100% identical), macaque AP1G1 (100% identical), rabbit AP1G1 (99% identical), mouse Ap1g1 (99% identical), rat Ap1g1 (99% identical), dog PHLPP2 (99% identical), pig AP1G1 (96% identical), tropical clawed frog ap1g1 (91% identical), zebrafish ap1g1 (90% identical), guinea pig AP1G1 (88% identical), Drosophila melanogaster AP-1gamma (55% identical), Caenorhabditis elegans apg-1 (50% identical). Paralogues in human: AP1G2 (59% identical), AP2A2 (27% identical), AP2A1 (27% identical), AP4E1 (25% identical).
Diseases named in the same sentence as AP1G1 in open-access papers:
AP1G1 is named in the same sentence as 29 diseases in open-access papers, as found by Europe PMC text mining. Sharing a sentence is not in itself a finding about the gene and the disease. The quoted sentences say what the papers report.
Intellectual disability (3 papers, 2023 to 2025). "Variants in the AP1G1 gene have recently been associated with Usmani‐Riazuddin syndrome, which comprises intellectual disability, epilepsy, and developmental delay." (PMID 38840441, 2025). "This study describes and characterizes another new missense variant (c.196G>A, p.Gly66Arg) in AP1G1 in a girl with intellectual disability and abnormal behavior, thus expanding the case history." (PMID 41226632, 2025). "Individuals of families with variants in the AP1G1 gene show clinical phenotypes common to neurodevelopmental disorders (NDD), including global developmental delay (GDD) and intellectual disability (ID), which varies from mild to severe." (PMID 37108275, 2023).
Neurodevelopmental delay (2 papers, 2021 to 2025). "AP1G1 plays an important role in the PI3K/AKT pathway, which is not only associated with cancers but also with megalencephaly, ASD, neurodevelopmental delay, and other NDDs." (PMID 33809095, 2021).
viral infection (2 papers, 2025). "The impact of itaconate-mediated regulation of AP1G1 and clathrin on viral invasion was further examined in three viral infections: H1N1, RSV, and HCoV-229E." (PMID 41212381, 2025). "During viral infection, AP1G1 localizes to the cell membrane, interacts with clathrin, and may thereby facilitate viral invasion." (PMID 41212381, 2025). "Immunofluorescence and Western blot analyses showed that, in both BEAS-2B cells and C128A BEAS-2B cells, the distribution of AP1G1 on the cell membrane increased following viral infection, indicating that the Cys128 site mutation alone does not affect AP1G1 subcellular localization." (PMID 41212381, 2025).
acute myeloid leukemia (1 paper, 2024). Acute myeloid leukemia (AML) is a group of neoplasms arising from precursor cells committed to the myeloid cell-line differentiation. "After normal tissues from TCGA and GTEx databases were matched, higher AP1G1 and SP1 gene expression levels were observed in acute myeloid leukemia (LAML) (p < 0.05) compared to normal tissues." (PMID 39056681, 2024).
bipolar disorder (1 paper, 2010). A disorder of the brain that causes unusual shifts in mood, energy, activity levels and the ability to carry out day-to-day tasks. "It has been found that many members in the same pathway of CCDC91 are associated with bipolar disorder, and its binding partner AP1G1 was up-regulated in the post-mortem cerebellum of schizophrenia patients." (PMID 20808825, 2010).
brain cancer (1 paper, 2024). A primary or metastatic malignant neoplasm affecting the brain. "AP1G1 expression is increased in various types of cancer, including head and neck, colorectal, breast, and brain cancer." (PMID 39056681, 2024). "The expression of AP1G1 was found to be increased in several types of cancers, including head and neck, colorectal, breast, and brain cancer." (PMID 39056681, 2024).
colon cancer (1 paper, 2023). "AP-1 complex subunit gamma-1 (AP1G1) takes part in developing colon cancer and in liver cancer." (PMID 36979661, 2023).
COVID-19 (1 paper, 2025). A disease caused by infection with severe acute respiratory syndrome coronavirus 2. "Through bidirectional genome-wide CRISPR screening, AP1G1 was identified as a crucial host-dependent factor for the viral entry of SARS-CoV-2, where it facilitates viral particles internalization and contributes to the pathogenesis of COVID-19, MERS-CoV, and seasonal HCoVs." (PMID 41212381, 2025).
emphysema (1 paper, 2021). "The cytosolic transport (RNF126, PLEKHJ1, VPS51, and AP1G1), target of rapamycin (mTOR) signaling (PIK3CA, STK11, RPS6KB2, and PRR5), regulation of translation, metabolic regulation, and apoptosis are involved in the percent emphysema-associated network." (PMID 34777474, 2021).
gastric cancer (1 paper, 2024). A primary or metastatic malignant neoplasm involving the stomach. "As reported, AP1G1 and SERTAD1 promote gastric cancer progression." (PMID 38600465, 2024).
hepatocellular carcinoma (1 paper, 2022). A malignant tumor that arises from hepatocytes. "A case here is that maternally expressed gene 3 promotes hepatocellular carcinoma by activating PI3K/AKT signaling pathway through regulating AP1G1." (PMID 35383533, 2022).
HIV-1 infection (1 paper, 2021). The type species of lentivirus and the etiologic agent of acquired immunodeficiency syndrome (AIDS). "In our study, miR-29-x was predicted to target the DETmR AP-1 complex subunit gamma-1 (AP1G1), which in mammals is known to affect HIV-1 infection by influencing the process of HIV-mediated CD4 internalization and targeting to lysosomes." (PMID 33808870, 2021).
lung carcinoma (1 paper, 2026). "A systematic multi-omics analysis was conducted for the eight AP-1 adaptor complex genes (AP1AR, AP1B1, AP1G1, AP1G2, AP1M1, AP1M2, AP1S1, and AP1S3) to characterize their roles in lung cancer." (PMID 41438582, 2026). "While several AP-1 adaptor subunits, such as AP1B1 and AP1G1, have been studied in cancer 11, 12, a systematic evaluation of the AP-1 adaptor family in lung cancer is lacking." (PMID 41438582, 2026).
microcephaly (1 paper, 2023). A congenital or acquired developmental disorder in which the circumference of the head is smaller than normal for the person's age and sex. "Patients with mutations in the AP1G1 subunit have been reported to exhibit a small head size and microcephaly; to determine whether ap1g1+/− fish display reduced head size, we measured body length and head size by taking anterior and posterior width measurements at 6 dpf." (PMID 37108275, 2023).
Parkinson disease (1 paper, 2025). A progressive degenerative disorder of the central nervous system characterized by loss of dopamine producing neurons in the substantia nigra and the presence of Lewy bodies in the substantia nigra and locus coeruleus. "In all three cases, WGS identified CNVs and confirmed zygosity and pathogenicity, resulting in genetic diagnoses of PRKN‐related Parkinson disease, TAOK1‐related neurodevelopmental disorder, and AP1G1‐related Usmani‐Riazuddin syndrome." (PMID 38840441, 2025).
cancer (4 papers, 2019 to 2024). A tumor composed of atypical neoplastic, often pleomorphic cells that invade other tissues. "In renal cancer, AP1G1 expression is downregulated in patient tumor tissues and suppresses cancer cell proliferation and migration." (PMID 34565296, 2021). "Five mutated gene variants that were transferred to the BRCA1-KO fibroblasts (BTN3A2, DDX51, LARP6, AP1G1 and COL18A1) were found to be also present as RNA variants following RNA sequencing of BRCA1-KO fibroblasts after exposure to cancer EVs." (PMID 31200749, 2019). "Studies have shown that AP1G1 and SP1 are more highly expressed in cancer tissues than in normal tissues, and both are related to the invasion and proliferation of cancer cells." (PMID 39056681, 2024). "To examine the gene expression of AP1G1 and SP1, we first used the TIMER database to analyze the levels of AP1G1 and SP1 in different cancers." (PMID 39056681, 2024). "Although the biological significance of increased AP1G1 expression in cancer is not yet clear, AP1G1 is known to play a critical role in early development." (PMID 39056681, 2024). "Further experiments are necessary to explore whether AP1G1 and SP1 play a precise role in these cancer types and to clarify the mechanism." (PMID 39056681, 2024). "AP1G1 and SP1 expression levels were upregulated in different types of human cancer." (PMID 39056681, 2024). "Taken together this suggest that AP1G1, or AP1 complex might play a role in an intrinsic defense mechanim against cancer." (PMID 34565296, 2021).
infection (1 paper, 2025). The state of being infected such as from the introduction of a foreign agent such as serum, vaccine, antigenic substance or organism. "It was found that itaconate binds to AP1G1 at Cys128, impairing its interaction with clathrin, which inhibits clathrin-mediated viral particle uptake and reduces cellular susceptibility to infection (i.e., the likelihood of cells being infected by viruses and undergoing infection)." (PMID 41212381, 2025). "It was observed that AP1G1 interacts with clathrin during infection by H1N1, RSV, and HCoV-229E, but not under uninfected conditions." (PMID 41212381, 2025).
AP1G1 also shares sentences with these, for which no sentence is quoted: developmental delay (2 papers); neurodevelopmental disorder (2); tumor (2); amyloid (1); atherosclerosis (1); endometrial cancer (1); epilepsy (1); genetic disorder (1); head and neck squamous cell carcinoma (1); liver cancer (1); megalencephaly (1); schizophrenia (1).